SLC2A1 (solute carrier family 2 member 1)
Diseases named in the same sentence as SLC2A1 in open-access papers (continued):
Sharing a sentence is not in itself a finding about the gene and the disease.
lung carcinoma (153 papers, 2003 to 2026). "Given its critical role in LUAD, we further explored the impact of the SLC2A1 gene and its encoded protein in lung cancer." (PMID 40276602, 2025). "SLC2A1 overexpression can promote the growth and proliferation of various tumor cells and is associated with poor prognosis in lung cancer." (PMID 37072786, 2023). "A recent study of lung cancer demonstrated that high SLC2A1 expression was associated with increased glucose uptake on PET-CT." (PMID 33735188, 2021). "Initially, the baseline expression levels of SLC2A1 protein were assessed in lung cancer H1299 and A549 cells, revealing relatively higher expression in A549." (PMID 40092704, 2025). "The most relevant GLUTs in cancer include GLUT1 (SLC2A1), GLUT3 (SLC2A3) and GLUT4 (SLC2A4), which are highly expressed in breast, CRC and lung cancers, with a high affinity for glucose and commonly associated with poor prognosis and therapy resistance." (PMID 41154605, 2025). "The E7 oncoprotein was also found to upregulate the expression levels of SLC2A1 protein and mRNA in lung cancer cells." (PMID 40821990, 2025). "Our results demonstrate that SLC2A1, as a participant in autophagy and lysosome-related processes, promotes proliferation and migration of lung cancer." (PMID 40092704, 2025). "The expression levels of the GLUT1 protein, encoded by the SLC2A1 gene, and the MCT4 protein, encoded by the SLC16A3 gene, were analyzed in both lung cancer and normal tissues." (PMID 40276602, 2025). "Genes KRT81, SPP1, PCDH7, SLC2A1, and TET1 were significantly upregulated in tumor tissues and associated with poor prognosis and survival, providing insights for exploring lung cancer biomarkers in future studies." (PMID 41415280, 2025). "KRT81, SPP1, PCDH7, SLC2A1, and TET1 are associated with poor prognosis and survival outcomes, providing novel insights for exploring lung cancer biomarkers." (PMID 41415280, 2025). "The results showed that SPP1, SLC2A1 was significantly highly expressed in the lung cancer cell, while AGER was in the opposite." (PMID 36782138, 2023). "It suggested that the mRNA expression of SLC2A1 was remarkably downregulated in the tumors of the plenti-199a lung cancer mice compared with that of the plenti-NC lung cancer mice." (PMID 35517408, 2022). "We used qRT-PCR to determine the mRNA level of SLC2A1 in NSCLC cell lines and it verified that the level of SLC2A1 was considered to be much higher in lung cancer cell lines than that in normal epithelial cell lines." (PMID 35517408, 2022). "In the case of lung cancer, SLC2A1 or GLUT1 was identified as an important marker associated with poor prognosis." (PMID 35121805, 2022). "These include glucose transporter 1 (Glut1, SLC2A1, P11166), a GLUT with high affinity for glucose and a HIF-1 target, which is associated with poor prognosis in many tumors including lung cancer." (PMID 33992777, 2021). "Usually, under the hypoxia circumstance, the fast metabolism of lung cancer cell needs more glucose uptake, which stimulate the VEGF-induced neoangiogenesis and activates SLC2A1 and A3 transcription which encodes GLUT1and GLUT3." (PMID 34227915, 2021). "Solute carrier family two member 1 (SLC2A1/GLUT1) was an important regulator of the glycolysis pathway and was found to have an increased expression in premalignant lesions and neoplasms of lung cancer patients due to tumors’ high demand of glucose." (PMID 35096011, 2021). "Kaplan–Meier plots demonstrate that the high levels of HK2, SLC2A1 (GLUT1), LDHA, and HIF1a expression were associated with poor survival of lung cancer patients." (PMID 34692483, 2021). "According to previous research, SLC2A1 appears to serve as an oncogene in a variety of malignancies, including lung cancer, pancreatic cancer, oral cancer, and so on." (PMID 34906142, 2021). "The SLC2A1 (also called glucose transporter type 1, GLUT1) gene is the primary glucose transporter gene in human lung cancer." (PMID 20540786, 2010).
lung carcinoma (continued). "The upregulation of SLC2A1 in the signature shows a development in the Warburg effect that can even occur in earlier tumor stages, which is consistent with alternate reports that link SLC2A1 to aggressive lung cancer behavior." (PMID 40563443, 2025). "For example, GLUT1 (encoded by solute carrier family 2 member 1 (SLC2A1)) is overexpressed in many malignant tumors, including uterine cancer, ovarian cancer, cervical cancer, and lung cancer, and its expression is reportedly associated with prognosis." (PMID 40805250, 2025). "GLUT1, also known as solute carrier family 2 (SLC2A1), is a common overregulated gene in lung cancer that might also function as a receptor for HTLV-1." (PMID 39228892, 2024). "SLC2A1 can suppress ferroptosis by stimulating SLC2A1 in lung cancer." (PMID 39311766, 2024). "Extending on our above findings, in DepMap RNA-seq datasets of ovarian and lung cancer cell line panels, the expression of SLC2A1 mRNA significantly and positively correlated with that of SMARCA2 and SMARCA4 in cells with low (bottom quartile) SMARCA4 or SMARCA2 expression, respectively." (PMID 37210563, 2023). "Downregulation of SLC2A1 can interfere with glycolysis in lung cancer cells." (PMID 36091041, 2022). "Concerning lung cancer, SLC2A1 was observed highly expressed in patients of Lung adenocarcinoma (LUAD) which its development could be inhibited by SLC2A1 through various molecular pathways." (PMID 35517408, 2022). "In addition, according to the database, SLC2A1 is significantly highly expressed in tissue samples and cell lines of NSCLC patients, and the high expression of SLC2A1 is negatively correlated with the overall survival rate of lung cancer patients." (PMID 35517408, 2022). "In previous studies, researchers used all-trans retinoic acid (ATRA) to treat different lung cancer cells and found that the most significant reduction in the transcription level of SLC2A1 was found in SLC2A1 and the genes in the same family, thus excluding other gene families." (PMID 36065306, 2022). "Previous work also revealed a role of SLC2A1 in the prognosis of metastasis in lung cancer." (PMID 30973670, 2019). "The protein expression of SLC2A1 was significantly decreased in BRCA, OV, LIHC, and lung cancer, while being increased in COAD, KIRC, UCEC, PAAD, HNSC, and GBM." (PMID 36712872, 2022). "Given the potential oncogenic role of SLC2A1 (GLUT1) in LUAD, we speculate whether indacaterol can affect the biological behavior of lung cancer cells by regulating SLC2A1 (GLUT1)." (PMID 40276602, 2025). "Similarly, in lung cancer, radioresistance-related signatures also predict patient outcomes and immune status, identifying TOP2A, CDH3, ASPM, CENPF, SLC2A1, and PRC1 as potential detection biomarkers for early lung cancer." (PMID 41041339, 2025). "Studies have reported a negative correlation between the up-regulation of SLC2A1 and the overall survival of lung cancer patients." (PMID 39275122, 2024). "Nutrient transporter SLC2A1 and SLC7A5 both exhibit cancer-promoting potential in lung cancer." (PMID 33129284, 2020). "Glucose transporter 1 (GLUT1) is a pivotal protein in the pathway of cellular energy metabolism, also known as solute carrier family 2 member 1 (SLC2A1); it has a particularly essential role in the occurrence and progression of tumors, and may be one of the driver genes of lung cancer." (PMID 34323652, 2021). "Moreover, protein levels of RRM2 were slightly reduced in either MTHFD2 or SLC2A1 knockdown lung cancer cells, but no alteration of MTHFD1 and SLC2A1 in RRM2 knockdown cells." (PMID 33664854, 2021).
Hyperglycemia (150 papers, 2007 to 2026). An increased concentration of glucose in the blood. "The same up-regulation of Slc2a1 was seen in the hearts of FH mice, supporting insulin resistance, and increased unregulated glucose uptake in the face of permanent hyperglycaemia in the remodelled myocardium of Foz mice with MASH." (PMID 39206703, 2024). "In normoxia hyperglycemia we observed significantly increased expression of glucose transporters SLC2A1 (nearly fourfold, p < 0.05) and SLC2A4 (more than sevenfold, p < 0.05) and PKM2 (p < 0.01)." (PMID 35328751, 2022). "Much of the early evidence suggested that hyperglycemia lowered GLUT1 (Slc2a1) expression, normalizing brain glucose transport." (PMID 30618559, 2018). "Thus, downregulation of SLC2A1 on brain blood vessels due to hyperglycemia could lead to metabolic changes in neural tissue leading to cognitive dysfunction especially after repeated hypoglycemic episodes." (PMID 30498224, 2018). "What is more critical, in our observations of WWOX KO fibroblasts in comparison to control in normoxia hyperglycemia, we stated that the SLC2A1 and SLC2A4 mRNA increase does not translate into protein level and glucose uptake growth." (PMID 35328751, 2022).
colorectal cancer (147 papers, 2009 to 2026). A primary or metastatic malignant neoplasm that affects the colon or rectum. "A recent study has found that high levels of methylation of the solute carrier family 2 member 1 (SLC2A1) gene in colorectal cancer patients are positively associated with the inhibition of ferroptosis and immunosuppression." (PMID 38392340, 2024). "Overall, these data indicate that the DNA methylation-associated silencing of DERL3 in HCT-116 colorectal cancer cells causes a pro-tumorigenic upregulation of the SLC2A1 protein that can be reversed by restoring DERL3 activity." (PMID 24699711, 2014). "IMP2 is a critical regulator of glycolysis in colorectal cancer, driving tumor progression by stabilizing m6A-modified mRNAs of key glycolytic enzymes, hexokinase 2 (encoding HK2) and SLC2A1 (encoding GLUT1)." (PMID 40141058, 2025). "SLC2A1 is also essential to IRI during liver transplantation and a diagnostic biomarker for colorectal cancer (CRC)." (PMID 36482897, 2022). "METTL3 stabilizes HK2 and SLC2A1 (GLUT1) expression in colorectal cancer and m6A-dependent glycolysis enhances colorectal cancer progression." (PMID 36249071, 2022). "Based on the 2020 TCGA data, the overexpression of HIF1α target genes VEGFA and SLC2A1 correlated with poor disease-free prognosis in colorectal cancer." (PMID 34686682, 2021). "The expression of selected genes related to MG degradation III (AKR1B10, AKR1C2 and ADH4), glyoxalase system (GLO1 and HAGH), glucose transport (SLC2A1 and SLC5A1) and colorectal cancer-associated genes (AREG, CXCL8 and CEACAM1) were quantitated using qRT-PCR." (PMID 32561807, 2020). "SLC2A1′s involvement in METTL3-mediated glycolysis has been observed in colorectal cancer." (PMID 39593730, 2024). "Colorectal cancer patients with high SLC2A1 expression have a poor prognosis." (PMID 38392340, 2024). "Similarly, IGF2BP2 stabilizes the HK2 and SLC2A1 mRNAs, and accelerates glycolytic metabolism and cell proliferation in colorectal cancer." (PMID 35299748, 2022). "However, there are few comprehensive studies on SLC2A1 in colorectal cancer (CRC)." (PMID 35399515, 2022). "Further, in colorectal cancer cells, it is shown that ZIC5 forms a complex with TCF7L2 and β‐catenin to act as a transcriptional repressor of SLC2A1." (PMID 40318167, 2025). "Previous research has established that increased SLC2A1 expression enhances the aggressiveness of hepatocellular carcinoma, LUAD, and colorectal cancer cells." (PMID 40824962, 2025). "A few DEPs have been previously reported as molecules connected with response to RT in colorectal cancer, including FGB, CD44, GLUT1/SLC2A1, PON1." (PMID 35205741, 2022). "METTL3 regulates colorectal cancer metastasis by enhancing the mRNA stability of SOX2, HK2 and SLC2A1 (GLUT1) through an m6A-IGF2BP2/3-dependent mechanism." (PMID 34094960, 2021). "METTL3 stabilized the expressions of HK2 (HGNC:4923) and SLC2A1 (HGNC:11005) in CRC through a m6A-IGF2BP2/3-dependent mechanism to regulate glycolytic pathways and promote colorectal cancer progression." (PMID 35087827, 2021). "Moreover, in colorectal cancer, METTL3 targets genes such as SOX2, HK2, SLC2A1, and CBX8, inducing metastasis-related processes and activating the glycolysis pathway and cellular stemness." (PMID 38966069, 2024). "METTL3 has been found to guarantee the stability of hexokinase 2 (HK2) and solute carrier family 2 member 1 (SLC2A1) via an m6A-insulin-like growth factor 2 mRNA-binding protein 2 (IGF2BP2)/3-dependent pathway, contributing to the tumorigenesis of colorectal cancer (CRC)." (PMID 35804965, 2022). "The researchers learned from the literature that SLC2A1 (GLUT1) and PKM2, as two popular SHK binding sites, have not been studied in colorectal cancer." (PMID 41272362, 2025).
epilepsy (128 papers, 2010 to 2026). A brain disorder characterized by episodes of abnormally increased neuronal discharge resulting in transient episodes of sensory or motor neurological dysfunction, or psychic dysfunction. "In humans, haplodeficiency of SLC2A1, encoding GLUT1, causes an autosomal dominant genetic disease named GLUT1 deficiency syndrome, manifesting primarily in neurological symptoms such as epilepsy and impaired development." (PMID 41226500, 2025). "Only few reports have addressed the causative role of SLC2A1 mutations in spastic paraparesis, direct or more often combined with complex phenotype, including paroxysmal exercise‐induced dyskinesia, ID, and epilepsy." (PMID 38803061, 2024). "Group 3 comprised patients for whom treatment with KD was introduced at V0 for reasons other than MD: drug-resistant epilepsy (n = 8) or deficiency of glucose transporter GLUT1 (pathogenic variant in gene SLC2A1) (n = 2)." (PMID 38542723, 2024). "In this study, 14 SLC2A1 heterozygous variants, including 13 de novo and one co-segregation, were identified in 16 epilepsy cases." (PMID 40217381, 2024). "The heterozygous missense variant c.493G > A (p.Val165Ile) in exon 4 of the SLC2A1 gene was identified in all family members showing epilepsy and/or PED episodes." (PMID 36362347, 2022). "The ketogenic diet was considered by respondents as early in the management of seizures as a second or third line therapy option, with few other epilepsies, e.g., SLC2A1 mutation, prompting such early consideration." (PMID 35795799, 2022). "It must be underlined that SLC2A1 was the most frequently altered gene in both comorbid and isolated epilepsy, and in the whole NDDs cohort irrespectively of the disease considered." (PMID 36035117, 2022). "The ketogenic diet can improve both epilepsy and PED episodes in SLC2A1 mutation carriers, and remains a therapeutic option for refractory epilepsy of various causes." (PMID 33833732, 2021). "By reanalyzing exome data, we identified a de novo heterozygous SLC2A1 variant in a girl with epilepsy." (PMID 34332575, 2021). "The third patient, a 28-year-old woman with early-onset developmental delay, epilepsy, and movement disorders was treated with a ketogenic diet following the identification of a variant in SLC2A1, confirming a glucose transporter type 1 deficiency syndrome." (PMID 34066437, 2021). "The translocation disrupts the interaction between SLC2A1, a gene associated with the seizure disorder GLUT1 deficiency syndrome, and several putative enhancer elements." (PMID 32973355, 2021). "SLC2A1 encodes GLUT1, the most prominent glucose transporter of the human brain and haploinsufficiency of SLC2A1 causes GLUT1 deficiency syndrome (GLUT1-DS), characterized by varying degrees of intellectual disability, epilepsy and movement disorders." (PMID 32899411, 2020). "GLUT1 deficiency syndrome is a treatable disorder of glucose transport into the brain caused by a variety of mutations in the SLC2A1 gene which are the cause of different neurological disorders including different types of epilepsy." (PMID 29303961, 2018). "Of note, allelic disorders associated with SLC2A1 mutations, glucose-deficiency syndrome, epilepsy, and dystonia, are associated with cognitive disability." (PMID 30498224, 2018). "This would be akin to epilepsy resulting from loss-of-function mutations in the facilitative glucose transporter GLUT1 (SLC2A1)." (PMID 28264506, 2017). "Recently, dominant SLC2A1 mutations were found in various forms of epilepsy, including genetic generalized epilepsy (GGE)." (PMID 28961260, 2017). "Four of the patients with SLC2A1 mutations had classical absence epilepsy, one had epilepsy with myoclonic absences, and one had been diagnosed with focal epilepsy, though this patient had generalized discharges on EEG." (PMID 28507422, 2017).